CYP3A4 (cytochrome P450 family 3 subfamily A member 4)
Diseases named in the same sentence as CYP3A4 in open-access papers (continued):
Sharing a sentence is not in itself a finding about the gene and the disease.
Hyperkalemia (5 papers, 2016 to 2026). An abnormally increased potassium concentration in the blood. "Cytochrome P450 3A4 (CYP3A4) inhibitors are pharmacokinetic precipitators that interact with most MRAs, except spironolactone, and adversely affect the risk of hyperkalemia, although suggestive evidence is scarce." (PMID 42196253, 2026).
injury (5 papers, 2021 to 2025). Damage inflicted on the body as the direct or indirect result of an external force, with or without disruption of structural continuity. "In this study, immortalized cells expressing CYP3A4 were generated from a patient with drug-induced liver injury (DILI)." (PMID 35012658, 2022). "We found that isopimpinellin could directly engage with targets such as NR1I2 and CYP3A4, which are central to the body’s response to oxidative liver injury." (PMID 38666923, 2024).
ischemic stroke (5 papers, 2020 to 2023). A stroke disorder caused by obstruction of blood flow to the brain, due to thrombotic (local blood clot formation) or embolic (due to a blood clot or other material traveling from another site) event. "This study aimed to investigate the roles of CYP3A4 and CYP11A1 variants in ischemic stroke (IS) susceptibility among the Han Chinese population." (PMID 32126981, 2020).
mucositis (5 papers, 2016 to 2023). Mucositis is inflammation and damage of the mucous membranes lining the mouth and other parts of the gastrointestinal (GI) tract. "Their metabolism is mediated by the CYP3A4 pathway; therefore, inhibition of the CYP3A4 pathway can increase blood concentrations of epipodophyllotoxins with an increased risk of mucositis, liver toxicity and myelosuppression." (PMID 27065862, 2016). "It is plausible that patients undergoing chemotherapy less likely experience sunlight exposure, less able to absorb Vit D due to subclinical mucositis and less able to metabolize 25(OH)D into inactive compounds such as 24,25(OH)2Vit D through the activation of CYP3A4 or other metabolizing enzymes." (PMID 28989587, 2017).
myocardial infarction (5 papers, 2016 to 2022). Gross necrosis of the myocardium, as a result of interruption of the blood supply to the area, as in coronary thrombosis. "We hypothesized that the risk of myocardial infarction could have been increased by the inhibition of CYP3A4 by sertraline, that leaded to increased concentration and side effects of sildenafil." (PMID 36133817, 2022). "Our study aims to assess the effects of the CYP3A4*22 allele and CYP3A5 expressor status in ticagrelor treated patients with a myocardial infarction, with respect to clinical endpoints and the most common side-effect dyspnea." (PMID 36545312, 2022). "Our study assessed the effects of the CYP3A4*22 allele and CYP3A5 expressor status in ticagrelor treated patients with a myocardial infarction, with respect to clinical endpoints and the side-effect dyspnea." (PMID 36545312, 2022).
renal dysfunction (5 papers, 2015 to 2025). "Ritonavir, which is administered to inhibit cytochrome P450 3A4 (CYP3A4), thus enhancing the effect of paritaprevir, was reported to have AUC values 114% higher in subjects with severe renal dysfunction than in control subjects." (PMID 29299684, 2018).
renal failure (5 papers, 2012 to 2024). "This study sought to determine single nucleotide polymorphisms in CYP3A5, CYP3A4 and MDR1 genes that affect the pharmacokinetics of Tacrolimus in a population of Ghanaian patients with kidney failure." (PMID 39080672, 2024). "This study described the allele and genotype frequencies of SNPs in CYP3A5, CYP3A4, and MDR1 genes that affect the pharmacokinetics of Tacrolimus in a population of Ghanaian patients with kidney failure." (PMID 39080672, 2024). "The reported SNPs of CYP3A4 in kidney failure patients in the present study may be important in tacrolimus dose requirement in transplant recipients." (PMID 39080672, 2024). "Most of the kidney failure patients in the present study harbored SNPs of CYP3A4, CYP3A5, MDR1 C3435T, and MDR1 G2677T, that could affect tacrolimus dose requirement in transplant recipients." (PMID 39080672, 2024). "SNPs in CYP3A4, CYP3A5, and MDR1 genes in a population of Ghanaian kidney failure patients were described." (PMID 39080672, 2024).
schizophrenia (5 papers, 2020 to 2025). A major psychotic disorder characterized by abnormalities in the perception or expression of reality. "In patients with schizophrenia (N = 96), development of clozapine concentration-dependent metabolic side-effects was found to be associated with pharmacokinetic variability related to CYP3A4 but not to CYP1A2 expression." (PMID 33277605, 2020). "In patients with schizophrenia, clozapine dosage is influenced by CYP1A2 activity, and tacrine metabolism is primarily dependent on the activity of CYP1A2 and CYP3A4 enzymes." (PMID 37759556, 2023). "Of note, if a patient with schizophrenia receives adjunctive antidepressants that are also metabolized by CYP2D6 and CYP3A4 (e.g., Fluoxetine, Paroxetine, etc.), increases in the serum concentrations of both the antidepressant and aripiprazole may occur." (PMID 40863247, 2025).
venous thromboembolism (5 papers, 2021 to 2026). Occlusion of the lumen of a vein by a thrombus that has migrated from a distal site via the blood stream. "The combined use of apixaban and inducers of CYP3A4 and/or P-gp was associated with an increased risk of venous thromboembolism (HR 1.58; 1.0–2.5)." (PMID 33029651, 2021). "In contrast, estrogen-containing contraceptives carry a higher baseline risk for venous thromboembolism and potential CYP3A4-mediated interactions, so they are generally less appropriate in women receiving BTK or BCL-2 inhibitors or in those with additional VTE risk factors." (PMID 41546716, 2026). "Association of TKIs and DOACs is common in cancer patients, to prevent venous thromboembolism, but TKIs’ influence upon P-gp and CYP3A4 affects DOAC (dabigatran, apixaban, rivaroxaban, edoxaban) plasmatic concentrations." (PMID 40732249, 2025).
AIDS (4 papers, 2006 to 2025). A syndrome resulting from the acquired deficiency of cellular immunity caused by the human immunodeficiency virus (HIV). "Ritonavir is a Cytochrome P450 3A4 (CYP3A4) protease inhibitor that has been used primarily to treat HIV/AIDS, with suggested applications in other diseases." (PMID 38175724, 2024). "Rifamycin derivatives such as RFP usually induce CYP3A4 enzymes, remarkably reducing the bioavailability of the drug itself as well as other CYP-intermediated drugs, including protease inhibitors, which are indispensable in the treatment of HIV/AIDS." (PMID 17132069, 2006). "Data on this CYP phenotype are crucial since differences in CYP3A4/5 frequencies could impact the PK of drugs like LPV and RTV, which are metabolized by this enzyme and which are commonly used in combination therapy for HIV/AIDS." (PMID 41150194, 2025).
Alzheimer disease (4 papers, 2014 to 2023). A progressive, neurodegenerative disease characterized by loss of function and death of nerve cells in several areas of the brain leading to loss of cognitive function such as memory and language. "This formula could improve the cognitive function of Alzheimer’s disease through CYP1A1 and CYP3A4 metabolism-related targets." (PMID 37764767, 2023).
Cachexia (4 papers, 2023 to 2024). Severe weight loss, wasting of muscle, loss of appetite, and general debility related to a chronic disease. "The main characteristics of cancer cachexia are anorexia and inflammation, and the elevated production of proinflammatory cytokines can cause a decrease in CYP3A4 activity, resulting in alterations in AZ7550 metabolism." (PMID 36637703, 2023). "Based on these findings, we propose that ACT may exert its anti-cachexia effects through the regulation of inflammatory response and energy metabolism via multiple targets, including CYP3A4, CYP19A1, CYP2E1, TNF, BCL-2, RYR2, and ATP2A1." (PMID 39872045, 2024). "Additionally, the authors proposed that cachexia-associated systemic inflammation, as indicated by increased CRP levels, may decrease CYP3A4 levels by downregulating its expression, possibly leading to increased plasma fentanyl concentrations." (PMID 39272951, 2024).
colitis (4 papers, 2020 to 2022). Inflammation of the colon. "The expression profile of PXR and its target gene Cyp3A4 mirror P-gp at baseline, and both are decreased in mouse models of colitis and human ulcerative colitis similar to P-gp." (PMID 35968955, 2022). "In support of the decreased cytochrome P450 activity in metabolomic result, we observed that CYP3A4 and CYP1A1 protein abundance was markedly reduced in the colon samples of colitis mice subjected to the CYN therapy." (PMID 36278202, 2022).
colon adenocarcinoma (4 papers, 2012 to 2024). "In particular, G. biloba extract at 200 μg/mL increased by 9.5-fold human PXR activation and the expression of PXR target genes, i.e., CYP3A4, CYP3A5 and ABCB1 (encoding P-gp) in human LS180 colon adenocarcinoma cells." (PMID 32635538, 2020). "In next series of experiments, the effects of OME and LAN on transcriptional activity of PXR, a key regulator of CYP3A4, were assessed in human colon adenocarcinoma cells LS174T transiently transfected with p3A4-luc reporter construct (for details see Materials and Methods section)." (PMID 25141173, 2014).
Hepatic steatosis (4 papers, 2012 to 2025). Steatosis is a term used to denote lipid accumulation within hepatocytes. "Our results demonstrate that CYP3A4 activity impairment is not only induced by hepatic steatosis but also a factor further promoting hepatic steatosis." (PMID 31191607, 2019). "CYP3A4, namely hepatic cytochrome P450 subfamily III A polypeptide 4, contributes to the metabolism of 45–60% of all drugs used in the clinical setting; its decreased expression and function were reported to be related to non−alcoholic fatty liver disease." (PMID 36496924, 2022).
nephrotic syndrome (4 papers, 2019 to 2025). A collection of symptoms that include severe edema, proteinuria, and hypoalbuminemia; it is indicative of renal dysfunction. "Therefore, we hypothesize that the observed spectrum of adverse events, including nephrotic syndrome as the most prominent one, during dasatinib therapy in our patient was influenced by transient phenoconversion of CYP3A4 enzyme." (PMID 31187953, 2019).
pancreatic cancer (4 papers, 2018 to 2023). "In pancreatic cancer cells, overexpression of miR-27b leads to downregulation of CYP3A4 protein and results in drug resistance to cyclophosphamide because CYP3A4 is necessary for drug activation." (PMID 29967761, 2018). "In the subgroup analysis using pancreatic cancer patients, only CYP3A4 inducers showed marginal significance in the multivariate analysis (p = 0.055)." (PMID 30326853, 2018). "Subgroup analysis using pancreatic cancer patients yielded marginally significant results with CYP3A4 inducers and erlotinib-induced hepatotoxicity." (PMID 30326853, 2018).
psoriasis (4 papers, 2019 to 2024). An autoimmune condition characterized by red, well-delineated plaques with silvery scales that are usually on the extensor surfaces and scalp. "Inhibition of CYP3A4 by Tribulus terrestris preparations was most likely associated with the increase in the concentration and the severity of side effects of citalopram (generalized pruritus), escitalopram (galactorrhea), and trazodone (psoriasis relapse)." (PMID 37829299, 2023). "In this study, we evaluated the inhibitory effects of a designed formulation on CYP3A4 protein expression and its therapeutic potential for psoriasis-like skin lesions." (PMID 37631230, 2023). "Desoximetasone (C22H29FO4; MW = 376.5), a substrate of CYP3A4, is a potent topical corticosteroid used to alleviate various skin conditions such as skin allergies, atopic dermatitis, and psoriasis." (PMID 37631230, 2023).
pulmonary hypertension (4 papers, 2017 to 2025). Increased pressure within the pulmonary circulation due to lung or heart disorder. "Bosentan, an endothelin receptor antagonist indicated for pulmonary arterial hypertension, is an inducer of CYP2C9 and a substrate for the same as well as inducer and a substrate for CYP3A4." (PMID 28249566, 2017). "Prior to changing pulmonary hypertension medications from bosentan to macitentan, bosentan could have increased the hepatic metabolism of warfarin by inducing CYP2C9 and CYP3A4 activity and decreasing its anticoagulant effects." (PMID 39993785, 2025).
acute lymphoblastic leukemia (3 papers, 2018 to 2026). Leukemia with an acute onset, characterized by the presence of lymphoblasts in the bone marrow and the peripheral blood. "Fluconazole is a weaker CYP3A4 inhibitor than other azoles and, specifically, fluconazole prophylaxis has been used in acute lymphoblastic leukaemia (ALL) induction chemotherapy, but there are no reliable data to support a recommendation for prophylaxis in this setting." (PMID 29218389, 2018).
alcoholic liver diseases (3 papers, 2021 to 2023). A disorder caused by damage to the liver parenchyma due to alcohol consumption. "The most prominent downregulation of metabolizing enzymes was associated with alcoholic liver disease (CYP1A2, CYP2C8, CYP2D6, CYP2E1, CYP3A4, UGT2B7) and primary biliary cholangitis (CYP1A1, CYP2B6, CYP2C8, CYP2E1, CYP3A4)." (PMID 37371728, 2023). "Alcoholic liver disease and primary biliary cholangitis were involved in the most prominent changes in the protein abundances, with downregulation of 6 (CYP1A2, CYP2C8, CYP2D6, CYP2E1, CYP3A4, UGT2B7) and 5 (CYP1A1, CYP2B6, CYP2C8, CYP2E1, CYP3A4) significantly downregulated enzymes, respectively." (PMID 34575411, 2021).
anemia (3 papers, 2019 to 2025). A reduction in the number of red blood cells, the amount of hemoglobin, and/or the volume of packed red blood cells. "During pregnancy, dose requirements increase by 25-50%, influenced by heightened CYP3A4 activity, increased plasma volume, hypoalbuminemia, and anemia." (PMID 40255720, 2025).
angina (3 papers, 2014 to 2024). "Ranolazine, used in the treatment of stable angina pectoris, is primarily cleared by CYP3A4 (70%-85%) and is a substrate of P-glycoprotein." (PMID 39219194, 2024). "Standard doses of ivabradine are indicated for treatment of angina as an alternative or in addition to beta-blockers, but should not be administered in association with CYP3A4 inhibitors or heart rate-lowering calcium-channel blockers." (PMID 29736470, 2016). "However, when patients receiving Diltiazem/Verapamil or strong CYP3A4 inhibitors are excluded from analysis, the difference between groups (with or without severe angina) and the harmful effect of Ivabradine among patients with severe angina disappear." (PMID 29736470, 2016).
anorexia nervosa (3 papers, 2018 to 2021). A disorder most often seen in adolescent females characterized by a refusal to maintain a minimally normal body weight, an intense fear of gaining weight, a disturbance in body image, and, in postmenarcheal females, the development of amenorrhea. "A preliminary study found that CYP3A4 enzyme activity was increased in patients with anorexia nervosa compared to a control group with normal weight, and that CYP3A4 activity was negatively correlated with body weight." (PMID 32529756, 2020). "In that study the CYP3A4 activity was also higher in underweight patients with anorexia nervosa than in a group of healthy, normal‐weight controls." (PMID 32529756, 2020). "In conclusion, in patients with anorexia nervosa, the metabolic activity of CYP3A4 decreased, whereas the metabolic activity of CYP1A2 might increase, with increasing BMI." (PMID 32529756, 2020). "In this study, 24 patients with anorexia nervosa at two occasions ingested single oral doses of five test drugs known to be metabolized by CYP1A2, CYP2C9, CYP2C19, CYP2D6, and CYP3A4, respectively." (PMID 32529756, 2020). "Due to the lack of information on the possible effect of low body weight on most CYP enzymes, the aim of this study was to explore whether changes in body weight in patients with anorexia nervosa affect the metabolic activity of the CYP enzymes CYP1A2, CYP2C9, CYP2C19, CYP2D6, and CYP3A4." (PMID 32529756, 2020). "Patients with anorexia nervosa have elevated concentrations of these cytokines, and if the increase in cytokine concentrations is sufficiently high to affect CYP enzyme activities, it could explain the possibly lower CYP1A2 activity, but not the increased CYP3A4 activity." (PMID 32529756, 2020).
autoimmune disease (3 papers, 2023 to 2024). A disorder resulting from loss of function or tissue destruction of an organ or multiple organs, arising from humoral or cellular immune responses of the individual to their own tissue constituents. "In terms of metabolism, as CYP3A4 is a crucial enzyme, the treatment of autoimmune diseases such as RA and cancer consequently involves the analysis of ADMET." (PMID 39189018, 2024).
celiac disease (3 papers, 2021 to 2022). An autoimmune genetic disorder with an unknown pattern of inheritance that primarily affects the digestive tract. "The findings about downregulation of CYP3A4 mRNA in the intestine in celiac disease has been reproduced in biopsy samples from the duodenum and ileum." (PMID 36359206, 2022). "Research into hepatic and intestinal CYP3A4 activities by means of intravenous and oral midazolam and budesonide in patients with Crohn’s disease and celiac disease has detected a marked drop of CYP3A4 activity in vivo in patients with celiac disease." (PMID 36359206, 2022). "CYP3A4 and I-FABP have previously shown promise as blood biomarkers in predicting duodenal damage in celiac disease." (PMID 34394117, 2021).
cholangiocarcinoma (3 papers, 2020 to 2023). A carcinoma that arises from the intrahepatic biliary tree (intrahepatic cholangiocarcinoma) or from the junction, or adjacent to the junction, of the right and left hepatic ducts (hilar cholangiocarcinoma). "An intrahepatic cholangiocarcinoma model with hepatocyte differentiation showed higher CYP3A4 activity and bile acid production." (PMID 36823159, 2023).
chronic myeloid leukemia (3 papers, 2003 to 2025). "Olverembatinib (HQP1351) is a third-generation BCR-ABL tyrosine kinase inhibitor for the treatment of chronic myeloid leukemia (CML) (including T315I-mutant disease), exhibits drug-drug interaction (DDI) potential through cytochrome P450 (CYP) enzymes CYP3A4, CYP2C9, CYP2C19, CYP1A2, and CYP2B6." (PMID 36582520, 2022).
congestive heart failure (3 papers, 2021 to 2022). Failure of the heart to pump a sufficient amount of blood to meet the needs of the body tissues, resulting in tissue congestion and edema. "IL-6 was further shown to suppress CYP1A2, CYP2B6, and CYP3A4 mRNA levels and to be associated with inhibited CYP3A4, CYP1A2, and CYP2C19 functioning (but not CYP2E or CYP2D6) in patients with cancer, congestive heart failure, or post-surgery." (PMID 34071813, 2021).
coronary artery disease (3 papers, 2020 to 2023). "Increase in serum HDL-C level: Genetic mutations in CYP3A4 and other five genes affected the therapeutic efficacy of atorvastatin in Indians, suffering from coronary artery disease." (PMID 37759317, 2023).
cystic fibrosis (3 papers, 2013 to 2026). Autosomal recessive disorder caused by pathogenic variants in the CFTR gene (cystic fibrosis transmembrane conductance regulator), which encodes a chloride and bicarbonate channel expressed in epithelial cells, and follow the diagnosis criteria. "Previous studies have shown that posaconazole can inhibit FK506 metabolism by cytochrome P450 (CYP3A4) in cystic fibrosis lung transplant patients to result in ∼3-fold increased levels of FK506." (PMID 23472097, 2013).
deep vein thrombosis (3 papers, 2019 to 2023). "When managing cancer-associated thrombosis (CAT), the concomitant use of a DOAC and a moderate or strong modulator (inhibitor or inducer) of CYP3A4 or a P-glycoprotein (P-gp) is most likely to be associated with significant DDIs." (PMID 35932318, 2022).